UNC93A (unc-93 homolog A)
Description:
Specifically transports N-acetylglucosamine across the plasma membrane.
Synonyms: Unc-93A; dJ366N23.2; dJ366N23.1
Tractability: Antibody: UniProt places it where antibodies can reach, with high confidence; its Gene Ontology location is reachable by antibodies, with high confidence; UniProt predicts a signal peptide or a membrane-spanning region.
Gene: Protein-coding gene on chromosome 6 (167,269,010 to 167,316,028, forward strand). Ensembl gene ENSG00000112494.
Subcellular location: Cell membrane
Gene Ontology:
Molecular function: N-acetylglucosamine transmembrane transporter activity; protein binding
Biological process: carbohydrate derivative transport
Cellular component: plasma membrane; membrane
Genetic constraint (gnomAD): Loss-of-function variants: 45 observed, 50.85 expected, observed/expected ratio (o/e) 0.88, 90% interval 0.7 to 1.13. The upper end of that interval is the gene's LOEUF score, 1.13, which puts it in group 4 of 6, group 1 being the genes least tolerant of losing a copy. Missense variants: 605 observed, 599.06 expected, observed/expected ratio (o/e) 1.01, 90% interval 0.94 to 1.08. Synonymous variants: 280 observed, 266.9 expected, observed/expected ratio (o/e) 1.05, 90% interval 0.95 to 1.16.
Homologues: Orthologues: chimpanzee UNC93A (89% identical), dog UNC93A (81% identical), macaque UNC93A (80% identical), pig UNC93A (78% identical), mouse Unc93a2 (72% identical), mouse Unc93a (72% identical), rat Unc93a (72% identical), guinea pig UNC93A (68% identical), rabbit UNC93A (59% identical), zebrafish unc93a (57% identical), tropical clawed frog unc93a.2 (57% identical), Drosophila melanogaster CG4928 (40% identical), and 2 more. Paralogues in human: UNC93B1 (24% identical).
Diseases named in the same sentence as UNC93A in open-access papers:
UNC93A is named in the same sentence as 9 diseases in open-access papers, as found by Europe PMC text mining. Sharing a sentence is not in itself a finding about the gene and the disease. The quoted sentences say what the papers report.
Alzheimer disease (1 paper, 2023). A progressive, neurodegenerative disease characterized by loss of function and death of nerve cells in several areas of the brain leading to loss of cognitive function such as memory and language. "To further confirm an association between the UNC93A and WDR27 variants and familial genetics risk for neurologic disorders, we analyzed their presence in unrelated healthy Peruvians (n = 50) and unrelated individuals with neurological disorders (probable Alzheimer’s disease, n = 8)." (PMID 36873109, 2023).
chronic kidney disease (1 paper, 2020). Impairment of the renal function secondary to chronic kidney damage persisting for three or more months. "Furthermore, the human UNC93A was recently identified as a metabolite-associated locus in chronic kidney disease patients." (PMID 33163493, 2020).
infection (1 paper, 2017). The state of being infected such as from the introduction of a foreign agent such as serum, vaccine, antigenic substance or organism. "In mammals, UNC93A and SV proteins are involved in intracellular transport and their transcripts were enriched more than 40-fold during Sindbis virus (SINV; Alphavirus; Togaviridae) or DENV2 infection of Ae. aegypti." (PMID 28506207, 2017).
neurological disorders (1 paper, 2023). "Several studies have also found SNPs in genes located on chromosome 6q with a significant connection to neurological diseases; however, the UNC93A and WDR27 variants have not yet been associated with ADRD." (PMID 36873109, 2023).
UNC93A also shares sentences with these, for which no sentence is quoted: genetic diseases (1 paper); heart failure (1); melanoma (1); metabolic syndrome (1); tumor (1).